SNORD39 (Small nucleolar RNA SNORD55/SNORD39 )
Synonyms: LOC124900282
Gene: Small nucleolar RNA gene on chromosome 9 (21,524,307 to 21,524,382, reverse strand). Ensembl gene ENSG00000264379.
Gene Ontology:
Biological process: RNA processing
Cellular component: nucleolus
Homologues: Orthologues: macaque SNORD39 (99% identical), guinea pig SNORD39 (58% identical), tropical clawed frog SNORD39 (54% identical), guinea pig SNORD39 (53% identical), tropical clawed frog SNORD39 (53% identical), guinea pig SNORD39 (50% identical). Paralogues in human: SNORD55 (75% identical), SNORD39 (61% identical), SNORD39 (53% identical).